SIGLECL1 (SIGLEC family like 1)
Synonyms: C19orf75; FLJ40235; SIGLEC23P; SIGLECP7
Tractability: Antibody: UniProt predicts a signal peptide or a membrane-spanning region.
Gene: Protein-coding gene on chromosome 19 (51,246,348 to 51,269,330, forward strand). Ensembl gene ENSG00000179213.
Subcellular location: Membrane
Gene Ontology:
Molecular function: protein binding
Cellular component: membrane
Genetic constraint (gnomAD): Loss-of-function variants: 17 observed, 21.96 expected, observed/expected ratio (o/e) 0.77, 90% interval 0.53 to 1.16. The upper end of that interval is the gene's LOEUF score, 1.16, which puts it in group 5 of 6, group 1 being the genes least tolerant of losing a copy. Missense variants: 210 observed, 250.84 expected, observed/expected ratio (o/e) 0.84, 90% interval 0.75 to 0.94. Synonymous variants: 89 observed, 94.73 expected, observed/expected ratio (o/e) 0.94, 90% interval 0.79 to 1.12.
Homologues: Orthologues: macaque SIGLECL1 (95% identical), dog SIGLECL1 (68% identical), rabbit SIGLECL1 (66% identical), mouse Siglecl1 (58% identical), rat Siglecl1 (56% identical). Paralogues in human: SIGLEC10 (26% identical), SIGLEC5 (24% identical), SIGLEC11 (22% identical), SIGLEC1 (17% identical), SIGLEC6 (16% identical), SIGLEC12 (16% identical), SIGLEC8 (16% identical), SIGLEC7 (15% identical), MAG (15% identical), SIGLEC9 (14% identical), SIGLEC14 (12% identical), TMEM25 (12% identical), and 4 more.